CD4 (CD4 molecule)
Diseases named in the same sentence as CD4 in open-access papers (continued):
Sharing a sentence is not in itself a finding about the gene and the disease.
infection (continued). "Pathogen-specific Tregs were induced by Mtb as demonstrated in a murine Mtb aerosol infection model, and these Tregs delayed priming of CD4+ and CD8+ T-cells in the pulmonary LNs, thereby delaying migration of these cells to the lung." (PMID 26029205, 2015). "With respect to these last two groups, there was no statistical difference in fungal burden, revealing that in the early phase of infection, the presence of CD4+ T cells per se can lead to a better fungal clearance." (PMID 26512987, 2015). "Apparently, F. hepatica would restrict the capacity of DCs to present antigens to CD4+ T cells as well as to prime specific CD4+ T cells, an effect that increases with persistence of infection." (PMID 26720149, 2015). "Th17 (CD4+IL-17+) cells were detected at day 1, peaked at day 3 post infection and then decreased gradually." (PMID 26230498, 2015). "The CXCR5−PD-1− CD4+ T cells appeared to be more resistant to infection (second row, far left panel)." (PMID 26034905, 2015). "The percent and the absolute number of CD4+Foxp3- T lymphocytes and of CD4+ T cells expressing Foxp3 in the lungs were determined by flow cytometry after 2 and 10 weeks of infection." (PMID 26512987, 2015). "The proliferative responses to SSAP of dermal CD4+ T cells recovered on day 4 after infection, from both 1x and 4x mice, were significantly greater than for cells recovered on day 1 (p<0.0001)." (PMID 25974019, 2015). "The mean levels of BLyS/BAFF expression by blood CD4+ T-cells increased significantly at three times points (days 8, 56–76 post-infection, and necropsy)." (PMID 26107380, 2015). "At week 2 post-infection, a more intense influx of activated/memory (CD44highCD62Llow) and naïve (CD44lowCD62Lhigh) CD4+ and CD8+ T lymphocytes was observed in the lungs of mice receiving anti-CD25 in comparison with IgG-treated mice." (PMID 26512987, 2015). "An interesting study on Salmonella infection in mice showed that peptide: MHC interaction in secondary lymphoid organs harboring bacteria for over 1 year after infection maintained the CD4+ TM cell population stable." (PMID 26509177, 2015). "Cumulative data of day 10 post infection from 8 donors shows that PD-L1 expression on HIV-infected CD4+ T cells (p24+) was significantly increased compared to p24- cells from the same cultures." (PMID 26484769, 2015). "We found comparable numbers of infiltrating CD8+ and CD4+ T cells in the liver tissue of infected Sod1−/− and WT mice at 24 hr after infection." (PMID 26588782, 2015). "The frequency of these triple producers increased with the progression of the infection until day 32 post-infection, when a maximum of approximately 30% of IL-21-producing CD4+ T cells co-expressed IFN-γ and IL-10." (PMID 25763578, 2015). "Exosomes can be used to protect against further infection, as shown in animal models by activating CD4+ T cells, and can be modified into effective vaccines." (PMID 26539170, 2015). "Following infection with L3 larvae of the intestinal helminth, H. polygyrus, we observed a significant expansion of Il4gfp+ CD4+ Th2 cells in the mesenteric lymph nodes 14 days post-infection." (PMID 26147567, 2015). "Dampening accumulation of highly activated CD4+ T cells by IL-27 signaling has also been recently observed in infection with other microorganisms, particularly intracellular protozoan and bacterial pathogens." (PMID 26222157, 2015). "SIVsmH4 Env-specific CD4+ and CD8+ T-cell responses, representative of env encoded in the Ad-recombinant, were comparable between immunization groups, and appeared post-infection in controls." (PMID 26267144, 2015). "By day 6 post infection, a shift occurred and CD4 and CD8 T cells were the majority of IFNγ producing cells in the spleen." (PMID 26070118, 2015). "We verified that CD11bhigh DCs sorted from Mtb-infected mice at 7 days post-infection induced significantly greater proliferation of both CD4+ and CD8+ T cells compared to CD11bhigh DCs sorted from non-infected mice." (PMID 26675186, 2015).
infection (continued). "Examples include the measurement of other less mutable core HIV components such as the p24 protein, cellular markers such as CD4, and blood metabolites such as hemoglobin all of which are important to monitor during active infection." (PMID 26457228, 2015). "The likelihood of infection after sexual exposure to HIV is heterogeneous and likely determined by availability of susceptible CD4 T cells at the site of exposure." (PMID 26335139, 2015). "In mice, after clearance of initial infection, tissue resident memory CD8 T cells lodge in the epidermis close to the site of infection but CD4 memory T cells are found deeper in the dermis and remain migratory." (PMID 25875649, 2015). "While previous studies have shown that RELM-β can modulate cytokine production by CD4+ T cells, this is the first study to show it recruits these cells to sites of injury/infection." (PMID 26285214, 2015). "Published studies indicate that increased non-R5 tropism frequency observed across the cohorts were associated with the higher number of late diagnosed patients and longer duration of the infection, lower baseline lymphocyte CD4 count and HIV subtype." (PMID 26297538, 2015). "The infection of C57BL/6 mice with LM induces a strong CD4+ T cell response with an elevated frequency of LLO-specific cells but a poor anti-LLO CD8+ T cell response." (PMID 25874208, 2015). "In contrast, a large proportion of CD4+CD25+ cells among the infiltrated CD4+ T cells were detected in the bursa of Fabricius of the IBDV-infected chickens upon infection with the Ts strain." (PMID 25803101, 2015). "The IIPs of the CD4 immunoadhesin reagents (CD4Im) reflected their differences in IC50, where eCD4-Ig achieved a 1.4 log greater reduction in infection than CD4-Ig (IIP=1.6±0.7 for CD4-Ig and 3.0±1.0 for eCD4-Ig, P<0.001)." (PMID 26416571, 2015). "Here we investigated the relationship between depletion and infection of CD4+ T cells in the lung parenchyma." (PMID 25933119, 2015). "CD4+ counts at ART initiation from a representative national cohort were used to estimate time since infection." (PMID 26302044, 2015). "The median % activation of CD4+ T lymphocytes on day 14 post SIVmac239 infection has been reported to be 20%." (PMID 25996507, 2015). "Trans-infection via MDDCs resulted in substantially higher levels (>10-fold) of CD4+ T-cell infection compared to direct infection of T-cells or MDDCs alone." (PMID 25809903, 2015). "Recent findings from our laboratory have demonstrated that following MCMV infection, regulatory T-cells are present within the CNS-infiltrating CD4+ T-lymphocyte population and accumulate within the brain from acute through chronic phases of infection." (PMID 26720146, 2015). "Intriguingly, double infection of CD4+ T cells occurred preferentially in memory CD4+ T cells—particularly the central memory (TCM) subset—but was not a consequence of SAMHD1-mediated restriction of HIV infection in naïve cells." (PMID 26559763, 2015). "In an activated CD4 T cell spreading infection model, the PGT121xCD3 MP3 or A32xCD3 MP3 DART increased neither the frequency of HIV-infected cells nor virus production following incubation for 5 days." (PMID 26539983, 2015). "Controls in the upper chamber included uninfected activated CD4+ T lymphocytes, whereas in the lower chamber comprehended resting CD4+ T lymphocytes either uninfected or treated with AZT at the time of infection." (PMID 26502902, 2015). "After secondary infection, d8, we also observed similar numbers (p>0.05) of both I-AbHA211 and I-AbNP311-specific CD4+ T cells in the MedLN and in the BAL." (PMID 26086392, 2015). "Here we demonstrate that Vpr and its cellular co-factor, DCAF1, are necessary for efficient cell-to-cell spread of HIV-1 from macrophages to CD4+ T lymphocytes when there is inadequate cell-free virus to support direct T lymphocyte infection." (PMID 26186441, 2015).
infection (continued). "7B2 IgG_AAA IgG1 mAb did reduce dissemination of infection from dendritic cells that emigrate from the tissue during the first 24 hours of culture on incubation with CD4+ indicator T cells." (PMID 26237403, 2015). "RMs of Indian origin were infected with SIVmac251 and sacrificed at different time points post infection to address the dynamics of CD4 and CD8 T cells, and B cells." (PMID 26640894, 2015). "Like in the mucosal transmission, the main targets of the infection are memory CD4+ T cells expressing the CCR5 receptor." (PMID 29061947, 2015). "Epigenetic mechanisms seem to play multiples roles in HIV latency, including HIV promoter silencing, transition of activated CD4+ T-cells to resting memory CD4+ T-cells, and post-transcriptional modifications during infection." (PMID 26347716, 2015). "T cell proliferation against parasite-derived antigens 70 days after infection was observed in CD98hcf/f-CD4 mice while strong responses in control mice." (PMID 26444422, 2015). "During natural infection, such conformational changes presumably follow the engagement of the cellular receptor, CD4, to form or expose the co-receptor binding site." (PMID 25569572, 2015). "Immunity to N. brasiliensis can be accelerated by adoptive transfer of CD4 T cells sensitised by primary infection into naïve mice." (PMID 25629518, 2015). "At the late phase of infection, mice receiving CD4+Foxp3- T cells or CD4+Foxp3- T cells + Treg cells showed significantly lower fungal burdens in the lungs when compared to mice given Treg cells or vehicle, besides very low dissemination to liver and spleen." (PMID 26512987, 2015). "Studies have indicated that LT-β is present on a variety of lymphoid cell types including plasma cells and a subpopulation of CD4+ T cells in tissues affected by chronic inflammatory disease or infection." (PMID 25874626, 2015). "We show that HIV latency can arise from the direct infection of both resting and activated CD4+ T cells." (PMID 26067822, 2015). "HIV-infected men having ≤500 CD4+ T-cells/mm3 had a higher prevalence of HPV16/18 infection than HIV-infected men with >500 cells/mm3 and HIV-uninfected men: 37% (23/63) vs. 24% (21/88) vs. 19% (36/189), respectively (Cochran-Armitage Test for Trend, p<0.01)." (PMID 25794147, 2015). "The generation of different CD4+ T cell subsets during infections is a very dynamic process, and activated CD4+ T cells, including Tfh cells, show substantial plasticity with overlapping phenotypes." (PMID 25763578, 2015). "We next determined if infection with multiple founder viruses is predictive of disease progression, as defined by CD4 count and viral load, in the context of heterosexual transmission in men and women in an HIV-1 subtype C setting." (PMID 25781986, 2015). "The resulting infection yielded a culture in which ∼10% of cells had a Gag+ CD4− phenotype, suggesting that surface CD4 was lost during the 3-day culture period." (PMID 26537682, 2015). "Knockdown of miR-125b-5p, miR-30c, and miR-182 led to a failure to control Cm infection and, in CD4−/− mice, levels of miR-125b-5p, miR-182, miR-183, and miR-135 were upregulated relative to wild-type infected mice." (PMID 26424969, 2015). "Which of these routes predominates in patients is not clear; however, HIV has mechanisms to prevent sequential infection at the cellular level, including Nef-mediated CD4+ down-regulation." (PMID 26559763, 2015). "Triple-cytokine-producing CD4+ T cells were detectable in the blood of all infected pigs from two weeks post primary infection onwards." (PMID 25971313, 2015). "Here we observed a higher expression of IL-17 in CD4+ T cells after the infection with both strains." (PMID 26147698, 2015). "By 120 days post-infection, the frequency and total numbers of IL-21-producing CD4+ T cells in the spleen were comparable to those observed in naïve WT C57BL/6 mice." (PMID 25763578, 2015).
infection (continued). "Despite the low frequency of infection by Col 1.7 and Y strains in CD4 and CD8 lymphocytes, these cells have a major role in orchestrating the immune response against the parasite and their activation depends on the interaction with infected monocytes." (PMID 26147698, 2015). "An increase in Ki-67 expression was noted at day 6 for CD4+ T cells in both age groups, with higher levels in old mice at both days 6 and 8 after infection." (PMID 26204259, 2015). "We next co-cultured CD4+ T cells with THP-1 cells expressing CD169 CT mutants to investigate the role of CD169 CT in mediating HIV-1 trans-infection." (PMID 25760631, 2015). "We also observed reduced accumulation of adult and old donor cells in the old compared to adult recipients, suggesting that the DLN environment separately contributed to the lower numbers of naïve CD4+ T cells recruited after infection." (PMID 26204259, 2015). "To assess the role of Vpx in infection of activated or unstimulated CD4+ T cells, we followed replication of an HIV-2 molecular clone, the GL-AN provirus, expressing or not the viral accessory protein (GL-AN WT and ∆Vpx, respectively)." (PMID 25582927, 2015). "The sum of our studies in humans and murine models of infection suggest that D4GDI produced by CD4+CD25+Foxp3+ T-cells has a previously undescribed positive effect on immunity by enhancing host antimicrobial activity." (PMID 25659138, 2015). "In contrast, following infection with the attenuated strain, the distribution of thymocytes favored the enhancement of DN and CD4 SP thymocytes while reducing the DP subset." (PMID 26417438, 2015). "Conversely, uninfected cells isolated from untreated resting CD4+ T cells contained 0.40% reactivatable provirus, but only 0.14% latently infected cells were identified in this cell population after the initial infection." (PMID 26067822, 2015). "IFN-γ+TNF-α+IL-2+ multifunctional CD4+ T cells were present in the blood of all infected animals at one or two weeks after primary infection and their frequency increased in four out of six animals after homologous secondary infection." (PMID 25971313, 2015). "Overall, CD4:CD8 ratio was steady during this early period of infection, with a heavy bias toward the ≤1.0 (abnormal) group (P = 2.2 × 10-16 in normality tests)." (PMID 26191056, 2015). "The number of CD4+ cells was maintained constant at 31 h and 44 h post-infection, while the number of CD8+ T cells was four and sixfold superior to those of CD4+ T cells at these respective time points." (PMID 25699034, 2015). "The majority of IL-21-producing CD4+ T cells in the spleens of WT C57BL/6 mice co-expressed IFN-γ; in particular at the peak of infection, when over 70% of the IL-21-producing CD4+ T cells in the spleen also expressed IFN-γ." (PMID 25763578, 2015). "In summary, it appears that following vaccination or infection, a pool of CD4+ memory T cells are mobilized from depot tissues (e.g. the bone marrow) and enter the blood stream." (PMID 26332995, 2015). "Of particular importance was that CD4+T cells in CRF01_AE infection was significantly lower than that in CRF07_BC infection during 5 years, similar to our previously small-scale study focusing on persons of age <25 years old." (PMID 26121491, 2015). "The percentages of splenic CD4(+) and CD11c(+) cells were increased in semi-immune mice on day 7 post-infection." (PMID 25626734, 2015). "Both CD4+Foxp3− effector cells and CD4+Foxp3+ Tregs responded to infection by expressing IL-17A in the draining axillary lymph nodes (ALN), cervical lymph nodes (CLN) and MOIL in infected mice." (PMID 25790134, 2015). "An alternative explanation, supported by in silico modeling, would imply that viral replication is limited by the number of available targets for infection, i.e. CD4+CCR5+ T cells." (PMID 26407077, 2015).
infection (continued). "In contrast, in our study, repeated exposures to cercariae led to regulation being evident early after infection, thus emphasizing the early role of antigen-specific CD4+ T cells in mediating immune regulation in sites of initial infection, such as the skin." (PMID 25974019, 2015). "While THP-1/CD169YF cells captured HIV-1 particles as efficiently as THP-1/CD169 cells, HIV-1 trans-infection of CD4+ T cells by THP-1/CD169YF cells was completely abrogated." (PMID 25760631, 2015). "The removal of CD4 T cells from mice prior to infection with LCMV cl 13, or the loss of CD4 T cells during progressive HIV infection leads to increased viral burden, immune dysregulation, and functional T cell exhaustion." (PMID 25590581, 2015). "At day 7 post-infection, a significant proportion of CD4+ T cells isolated from the spleen of dnRara mice were IL-17+ or dual IL-17A+IFN-γ+ with a trend toward reduced frequency of IFN-γ+ cells." (PMID 25769610, 2015). "In this study, we used T/F virus enumeration as a measure of relative protection from infection along with VL set point and CD4 preservation." (PMID 26237403, 2015). "It has previously been shown that CTC5 inhibits HIV-1 entry in CCR5 transfected CD4+ cell lines and CD4+ T cells, and we now show that this antibody reduced infection of MDMs." (PMID 25957306, 2015). "The phosphorylation of STAT1 was notably reduced in CD4+ T cells in the FeD mice on day 7 post-infection." (PMID 25768944, 2015). "Depletion of Tregs resulted in increased proliferation of both CD8+ and CD4+ T-cell subsets within the brain at 14 d post infection (dpi) when compared to Treg-sufficient animals." (PMID 26720146, 2015). "In respect to controls, knockout lungs had approximately 3 x 105 and 1 x 105 more CD4+ EdU+ T cells in the lungs on days 6 and 8 post-infection, respectively." (PMID 26709698, 2015). "The evaluation of the mesenteric lymph nodes from the IP infected animals after 11 days of infection showed a reduction in CD4+ and CD8+ when this mice where compared to the controls." (PMID 26469517, 2015). "Aucune corrélation importante du point de vue statistique n'a été trouvée entre l'infection par les helminthes intestinaux et le nombre moyen de CD4 (p = 0.79) ou la charge virale moyenne (p = 0.98)." (PMID 26842519, 2015). "In summary, we demonstrate that repeated exposures of the skin to infective S. mansoni cercariae leads to an early increase in IL-10 production by S. mansoni specific CD4+ T cells in the dermis, with a putative Th2 bias, at the site of infection." (PMID 25974019, 2015). "We further show that resting CD4+ T cells from human lymphoid tissue (tonsil, spleen) show increased latency after infection when compared to peripheral blood." (PMID 26067822, 2015). "Postactivation latency refers to direct infection of activated CD4 T cell population, where viral production results in depletion of infected cells, but some revert to a resting stage containing HIV-1-integrated provirus." (PMID 25573791, 2015). "In order to calculate the sizes of the infected, ‘low CD4’ populations at equilibrium for both strains, we now introduce an infection-age-dependent model (which we will refer to as the ‘PDE model’) and relate it back to the original ODE model." (PMID 26609066, 2015). "Multiple components of cell-mediated immunity were increased in response to infection, including activated and inflammatory CD4+ TH cells." (PMID 26494419, 2015). "Several studies have demonstrated selection for CD4+ T cell clonotypes with stronger pMHCII tetramer binding or functional avidity during memory formation in response to immunization or infection." (PMID 26322045, 2015). "It is also possible that NKT cells including iNKT cells can play variable roles in different conditions or stages of infection, same as other cell types like CD4 and CD8 T cells." (PMID 26029217, 2015).